PLAC1 (placenta associated 1)
Diseases named in the same sentence as PLAC1 in open-access papers (continued):
Sharing a sentence is not in itself a finding about the gene and the disease.
cancer (continued). "Antibodies against survivin, livin, and PLAC1 are detected in sera across various cancer types." (PMID 38707901, 2024). "The placenta-specific protein-1 (PLAC-1) is part of the denominated cancer/testis antigens." (PMID 36016136, 2022). "PLAC1 is a cancer/testis antigen with a significant role in cancer progression and invasion." (PMID 31952435, 2020). "Notably, FGF7 plays an important role in regulating the growth of the mammary epithelium and also contributes to mammary tumorigenesis, a cancer type in which PLAC1 is found to be frequently expressed." (PMID 32499871, 2020). "PLAC1 protein is mainly expressed in placenta 9–12, while it is frequently activated in a variety of cancers including cancers of breast 13–16, lung 13–15,17,18, liver 14,17,19, colon 14,15,17,20–22, stomach 13,23,24, ovary 13,25,26, uterus 27,28, cervix 14,29, pancreas 30, and prostate 31,32." (PMID 32153735, 2020). "We then screened human cancer cell lines for PLAC1 and FGFR2 expression by Western Blot analysis." (PMID 32499871, 2020). "PLAC1 shows low normal tissue expression, but also demonstrates low overall prevalence in cancer." (PMID 33087697, 2020). "Plac1 however is re-expressed in several solid tumors and in most human cancer cell lines." (PMID 29632317, 2018). "Moreover, Plac1 possesses cancer‐specific immunogenicity that makes it a potential target for cancer immunotherapy." (PMID 29704427, 2018). "Previous studies have demonstrated that Plac1 could be a promising biomarker for the diagnosis and prognosis of many cancers." (PMID 29704427, 2018). "Such a rapid internalization kinetic together with high specificity could potentially compensate for low surface expression of PLAC1 and implies that 2H12C12 could function as a vehicle to deliver a drug payload to the PLAC1 positive cancer cells." (PMID 29042604, 2017). "In addition, PLAC1 expression has been reported in nearly one hundred human cancer cultured cell lines representing fourteen different cancers." (PMID 24757447, 2014). "Moreover, we found previously that PLAC1 is a critical factor for cancer cell proliferation, as silencing of PLAC1 results in a pronounced G1 cell cycle arrest accompanied by decreased cyclin D1 expression and hypophosphorylation of AKT kinase." (PMID 24304549, 2013). "In addition, PLAC1 expression has been demonstrated in nearly one hundred cancer cell lines representing fourteen different cancers." (PMID 23935632, 2013). "PLAC1, reported to be the first member of a new class of antigens that specifically relates placentation to cancer, has been observed to be ectopically activated in many human cancers and is essentially involved in malignant cell processes." (PMID 23206989, 2012). "The expression of PLAC1 in cancer cells also induces cellular and humoral immune responses via activation of cytotoxic T cells and antibody responses to antigen-presenting cells that carry PLAC1-derived peptides, which leads to the elimination of PLAC1-positive cancer cells." (PMID 32499871, 2020). "However, the clinical significance and mechanism of Plac1 in cancer progression remain elusive." (PMID 29704427, 2018). "To this end, we hypothesized that utilizing advantages of cancer cell specificity of anti-PLAC1 antibodies and cytotoxic activity of a chemically supertoxic agent could be considered an ideal approach for generation of an antibody drug conjugate (ADC) platform for targeted immunotherapy of PCa." (PMID 29042604, 2017). "In addition PLAC1 expression has been detected in a number of human cancers and cancer cell lines." (PMID 24757447, 2014). "In this study, we performed integrative bulk RNA‐seq and scRNA‐seq data analysis of HNSCC and revealed a special CTA, Placenta specific protein 1 (Plac1), is highly expressed in HNSCC cancer cells." (PMID 40056047, 2025). "Placenta-specific 1 (PLAC1), as a new Cancer/Testis Antigen (CTA), is frequently expressed in a variety of cancers and localized to cytoplasm and plasma membrane." (PMID 32153735, 2020).
cancer (continued). "In summary, our data confirmed co-expression of PLAC1 and FGFR2 in both the placental syncytiotrophoblast and in human cancer cell lines, and demonstrated that PLAC1 is a secreted protein, which accumulates in the ECM." (PMID 32499871, 2020). "This search yielded nine additional genes, including placenta-specific 1 (PLAC1), previously identified as a target of humoral antitumor immunity in cancer patients." (PMID 33087697, 2020). "Because AKT activation leads to increased cell proliferation, we evaluated whether PLAC1, as a co-factor of the FGF7-FGFR2 signaling pathway, also mediated cancer cell proliferation." (PMID 32499871, 2020). "Studies have revealed that PLAC1 expression in normal cells is not adequate to be measured, while its expression in cancer cells is measurable." (PMID 31952435, 2020). "Notably, PLAC1 is not expressed in other normal tissues but is detectable in a variety of cancers, making it an attractive target for cancer research due to its restricted expression pattern and immunogenic potential." (PMID 40607388, 2025). "However, the molecular pathways in which PLAC-1 participates in the trophoblastic invasion and differentiation with similar processes in cancer cells are not totally clear." (PMID 33916290, 2021). "Thus, despite trophoblastic cells, PLAC-1 is not found in healthy and differentiated cells except for some cancer cells." (PMID 33916290, 2021).
tumor (25 papers, 2011 to 2025). "Plac1 is associated with epithelial–mesenchymal transition and tumor invasion." (PMID 35814442, 2022). "The results of our study of clinical samples demonstrated that Plac1 expression might be associated with tumor invasion and metastasis." (PMID 29704427, 2018). "Overall, these data suggest that PLAC1 may have diagnostic value as a tumor-selective biomarker in breast and other malignancies." (PMID 29432428, 2018). "After CD4+ T cells infiltrate the TME, they interact with Plac1+ tumor cells via direct cell‐cell communication." (PMID 40056047, 2025). "In summary, we identified Plac1 as an HNSCC‐specific CTA whose expression is restricted to HNSCC tumor cells and is associated with advanced tumor stages and poor clinical outcomes." (PMID 40056047, 2025). "To validate the correlation of Plac1+ tumor cells with CD4+ T cells, we performed an IHC assay in the in‐house TMA cohort." (PMID 40056047, 2025). "Then, it is revealed that Plac1+ tumor cells recruit CD4+ T cells via CXCL11/CXCR3 and induce Treg differentiation via PVR/TIGIT, which in turn activates the tumorigenic signaling of Plac1+ tumor cells via LTA/LTBR and forms a reciprocal protumor loop." (PMID 40056047, 2025). "Unlike stress-induced activation mechanisms such as MICA/B or ULBPs, PLAC1 offers an additional interaction with NK cells, potentially enhancing tumor recognition and killing." (PMID 40607388, 2025). "This study identifies a novel role of PLAC1 as a potential ligand for NKARs, contributing to the recognition of tumor cells by NK cells." (PMID 40607388, 2025). "In contrast, PLAC1 is significantly upregulated in a wide range of tumor types compared to their normal tissue counterparts." (PMID 40607388, 2025). "The potential importance of PLAC1, compared to other tumor-mediated NK cell regulation mechanisms, lies in its role as a direct ligand for NKARs." (PMID 40607388, 2025). "Our study revealed that Plac1 functions as a key tumor‐promoting and immunoregulatory CTA gene in HNSCC." (PMID 40056047, 2025). "In the meantime, Plac1+ tumor cells shape a Treg‐related immunosuppressive microenvironment via CXCL11/CXCR3 and PVR/TIGIT, which in turn activates the tumorigenic signaling of Plac1+ tumor cells via LTA/LTBR and forms a reciprocal protumor loop." (PMID 40056047, 2025). "Neutralizing CD8+ T cells enhanced the tumor‐promoting effects of Plac1‐OE cells (tumor volume: p = 0.0432, tumor weight: p = 0.0354), which suggested that the antitumor cytotoxicity of CD8+ T cells inhibited tumor growth." (PMID 40056047, 2025). "PLAC1 is associated with placental development, TCF7 is involved in T cell differentiation, and PLEKHA5 has been linked to the suppression of tumor metastasis." (PMID 40607388, 2025). "To further explore the role of PLAC1 in NK cell activation, we analyzed its correlation with a NK cell gene signature in tumor types where PLAC1 expression affects overall survival of patients." (PMID 40607388, 2025). "We then identified a subpopulation of tumor cells that expresses Plac1 and termed them “Plac1+ tumor cells”." (PMID 40056047, 2025). "We found that the degree of tumor invasion was markedly alleviated by Plac1 ablation, as confirmed by H&E staining (p < 0.0001)." (PMID 40056047, 2025). "As shown by the bulk RNA‐seq data, Plac1 was more highly expressed in tumor tissues (T) than in normal tissues (NT), which reflects the common expression pattern of CTAs." (PMID 40056047, 2025). "Anti‐CD4 and anti‐CD8 neutralizing antibodies were administered to evaluate how CD4+ T or CD8+ T influenced the tumor‐promoting effects of Plac1 expression." (PMID 40056047, 2025). "The ST samples were also analyzed to investigate Plac1 expression pattern in HNSCC and we found that Plac1 expression was restricted in the tumor cells." (PMID 40056047, 2025).
tumor (continued). "Consistent with the subcutaneous tumor model, tumors grew rapidly in the Plac1‐OE group and the weights of mice in this group decreased more dramatically than those of Plac1‐NC group (p = 0.0074)." (PMID 40056047, 2025). "For example, how Plac1 expression enhances caveolae‐related gene upregulation, and how Plac1+ tumor cells secrete higher concentrations of CXCL11 and express higher levels of PVR." (PMID 40056047, 2025). "In the current study, tumorigenic Plac1+ tumor cells were demonstrated to enhance protumor signaling pathways and to accelerate tumor growth in in vitro and in vivo HNSCC models." (PMID 40056047, 2025). "Both the degree of invasion (p < 0.0001) and the ratio of proliferating tumor cell (p = 0.0198) were also significantly decreased in Plac1‐CKO mice." (PMID 40056047, 2025). "Subsequently, we assessed the expression of the PLAC-1 molecule in both enriched cells and parental tumor cells at the gene and protein levels using the same techniques." (PMID 38943028, 2024). "Effective engineering of CD8 + T cells to express TCRs that recognize human leukocyte antigen (HLA) -restricted PLAC1 peptides can specifically kill tumor cells overexpressing PLAC1." (PMID 37691919, 2023). "PLAC1 and Netrin-1 can become important markers for judging tumor metastasis, and can also be potential targets for the treatment of CRC." (PMID 37568074, 2023). "During embryo implantation, the trophocyte invasion into the endometrium and blood vessel formation is influenced by PLAC-1, which is very similar to the growth, invasion, and migration of tumours." (PMID 33916290, 2021). "In these types of tumours, PLAC-1 is directly related to tumorigenesis and aggressiveness, which are involved in the processes of cellular proliferation, migration, and invasion." (PMID 33916290, 2021). "Recently, it has been displayed that PLAC1 plays a critical role in tumor invasion and metastasis through Furin/NICD/PTEN/AKT axis." (PMID 31952435, 2020). "The effect of PLAC1 knockdown on constitutively active mutant AKT expressed in tumor cells warrants investigation." (PMID 32499871, 2020). "This study provides new insights into the role of PLAC1 in tumor cells and in placental syncytiotrophoblasts." (PMID 32499871, 2020). "In conclusion, this study demonstrates the contribution of PLAC1 to cell proliferation in placental and tumor tissues." (PMID 32499871, 2020). "This study investigated and characterized the link between PLAC1 and the FGF7/FGFR2IIIb signaling axis, and evaluated the potential role of PLAC1 in tumor cells." (PMID 32499871, 2020). "A rescue study showed that inhibition of Furin and overexpression of PTEN in Plac1 overexpression cells blocked Plac1‐induced tumor cell progression." (PMID 29704427, 2018). "Our current functional studies indicate that Plac1 has an oncogenic role to promote tumor migration and invasion, which is consistent with the results from a previous study." (PMID 29704427, 2018). "Our data strongly demonstrate that Plac1 promotes tumor cell invasion and metastasis through Furin/NICD/PTEN signaling pathway." (PMID 29704427, 2018). "Emerging evidence has indicated that Plac1 is involved in regulation of tumor metastasis and progression." (PMID 29704427, 2018). "Since Cxcl1 exhibited the greatest change in expression among all chemokine genes after Plac1 downregulation, mice were treated with a Cxcr2 antagonist to determine if it would affect tumor growth to a similar extent." (PMID 29632317, 2018). "In this regard, we noted previously in MMTV-PPARd transgenic mice that PLAC1 RNA and protein were markedly upregulated at the onset and throughout tumor development, and were reduced following treatment with the mTOR inhibitor everolimus." (PMID 29432428, 2018). "This multivariate statistical analysis was adjusted for LNM, Plac1 level, tumor size, gender, age, and HER2 and HR status." (PMID 29704427, 2018).
tumor (continued). "Results of experimental metastasis models showed that Plac1 overexpression in MDA‐MB‐231 cells significantly increased liver colonization of tumor cells." (PMID 29704427, 2018). "Our team is studying the monoclonal antibody against Plac1 to determine its potential to inhibit tumor metastasis." (PMID 29704427, 2018). "Cxcl1 KD phenocopied the effects of Plac1 KD on tumor growth, and overexpression of Cxcl1 partially rescued Plac1 KD cells." (PMID 29632317, 2018). "PLAC1’s higher level of expression in EBV positive MutuI cells relative to EBV negative Mutu cells led us to test the expression PLAC1 in a panel of tumor cell lines." (PMID 24912876, 2014). "Using RNAs isolated from primary matched tumor and normal tissues, we further determined a higher level of PLAC1 expression is some tumor samples." (PMID 24912876, 2014). "When tumor stage is considered, Stage 3 tumors display 10.41-fold higher PLAC1 expression than do Stage 1 and 2 tumors (P < 0.01)." (PMID 23935632, 2013). "Second, placenta- and tumor-specific PLAC1 expression, which was down-regulated by SOX2 over-expression, was significantly up-regulated by SOX2 knockdown with Pre-miR-126 and siRNA in HSC43 cells." (PMID 21304604, 2011). "In Plac1‐CKO mice, proliferating cells were restricted mainly to the basal layer of the epithelium, whereas proliferating cells were widely distributed in dysplasia and tumor lesions in Plac1‐WT mice, which presented a greater cell proliferation ratio than Plac1‐CKO mice (p = 0.0011)." (PMID 40056047, 2025). "Overall, we delineated cell–cell interaction landscape of tumor cells and immune cells and revealed that Plac1+ tumor cells recruited CD4+ T cells through the CXCL11/CXCR3 axis and then induced Treg differentiation through PVR/TIGIT to shape the immunosuppressive TME of HNSCC." (PMID 40056047, 2025). "In summary, these results suggest that, like its role in the embryonic microenvironment, SP1 might be involved in the expression of Plac1 during tumor initiation and progression." (PMID 40056047, 2025). "According to the tumor inhibition effects of Plac1 ablation, we were interested in whether Plac1 deletion could inhibit HNSCC growth when Plac1 expression was already increased in tumor cells." (PMID 40056047, 2025). "With in vitro experiments, in vivo subcutaneous tumor, and a transgenic autochthonous tumor model, it is revealed that Plac1 expression promotes HNSCC progression by inducing epidermal growth factor receptor endocytosis and recycling to increase PI3K/AKT signaling pathway activity." (PMID 40056047, 2025). "Moreover, the in‐house scRNA‐seq cohort included HNSCC tumor samples representing different clinical stages and Plac1 was significant more highly expressed in malignant epithelial cells from A‐stage samples." (PMID 40056047, 2025). "This interaction enhances NK cell-mediated cytotoxicity against PLAC1-expressing tumor cells." (PMID 40607388, 2025). "In the present study, we found that Tregs in the TME of HNSCC could secrete LTA, interacting with its receptor LTBR on Plac1+ tumor cells and activating the downstream PI3K/AKT signaling pathway to promote HNSCC cell proliferation, migration, and invasion." (PMID 40056047, 2025). "Using a subcutaneous tumor xenograft model in immune‐competent mice (C3H/HeJ), we evaluated whether Plac1 expression promoted HNSCC and shaped an immunosuppressive microenvironment in vivo." (PMID 40056047, 2025). "In conclusion, in the Plac1+ tumor cell‐Treg interaction, Tregs could enhance the malignant characteristics of Plac1+ tumor cells through the LTA/LTBR axis and by PI3K/AKT pathway activation." (PMID 40056047, 2025). "In the present study, we identified a specific CTA gene expressed in HNSCC tumor cells, Plac1." (PMID 40056047, 2025). "In contrast, these correlations were absent in tumor types where high PLAC1 expression was associated with poorer survival outcomes (BLCA, CESC, CHOL, COAD, HNSC, KIRC and PRAD)." (PMID 40607388, 2025).